KLRB1 (killer cell lectin like receptor B1)
Diseases named in the same sentence as KLRB1 in open-access papers (continued):
Sharing a sentence is not in itself a finding about the gene and the disease.
tumor (continued). "Therefore, up-regulated SLC27A2, KLRB1, IGKV1OR2-108 and IGHV1-12 in the low-risk score group synergistically inhibit tumor progression and activating immune response by regulating CD8+ T cells, NK cells and immunoglobulin." (PMID 36869083, 2023). "However, the role of KLRB1 in tumorigenesis and tumor development remains elusive from the perspective across multiple cancers." (PMID 35028320, 2022). "Patients with high expression of KLRB1 appeared to have higher levels of macrophages in the tumor." (PMID 35028320, 2022). "Eleven cancers showed significant differences in KLRB1 expression between normal and tumor samples." (PMID 35028320, 2022). "The expression of KLRB1 can affect tumor immune cell infiltration." (PMID 35028320, 2022). "However, the current research on the value of KLRB1 in tumor immunity and prognosis has concerned only a small number of cancers." (PMID 35028320, 2022). "We compared KLRB1 expression levels between tumor and normal tissues, according to TCGA database." (PMID 35028320, 2022). "We also found that KLRB1 may affect tumor immunity by affecting the levels of infiltrating immune-related cells, especially macrophages and lymphoid cells." (PMID 35028320, 2022). "Our results indicated that the expression of KLRB1 was negatively correlated with the degree of infiltration of cancer-promoting myeloid cells, while it was positively correlated with the degree of infiltration of tumor suppressor myeloid cells." (PMID 35028320, 2022). "A recent study has discovered that the knockdown of KLRB1 or antibody-mediated blockade of CD161 enhances the ability of T cells to kill tumor cells, suggesting that the CD161-LLT1 pathway may serve as a potential target of immunotherapy for glioma." (PMID 36246587, 2022). "Therefore, the assessment of the ability of KLRB1 to predict tumor immunity and predict immunotherapy response is based on indirect evidence." (PMID 35028320, 2022). "Furthermore, our GSEA findings showed that KLRB1 is highly enriched in the tumor T cell receptor signaling pathway, B cell receptor signaling pathway, antigen processing and presentation, and in other immune-related pathways." (PMID 35028320, 2022). "Using tumor-specific T cells co-cultured with gliomaspheres (3-dimensional clusters of tumor cells derived from human patients), investigators showed that inactivation of KLRB1 resulted in increased cytotoxic activity." (PMID 34868044, 2021). "CD161, encoded by KLRB1, is newly reported as a candidate inhibitor of tumour-infiltrating T cells." (PMID 34305920, 2021). "By using CRISPR-Cas9 technology to edit the KLRB1 gene in human T cell co-culture experiments and humanized glioblastoma mouse models to inhibit this pathway, not only was T cell-mediated cytotoxicity enhanced, but tumor growth was also slowed and survival was prolonged." (PMID 40895554, 2025). "Notably, the CD8_Tem-GZMK subset was relatively closer to the CD8_Tex-LAYN subset compared to the CD8_Tn-LEF1 and CD8_Trm-KLRB1 subsets, aligning with recent studies that highlight the transition from effector memory T cells to exhausted T cells during tumor progression." (PMID 38596689, 2024). "The outcomes of GSEA highlighted that the group with over-expression of KLRB1 was mainly concentrated in the cell adhesion, and signaling pathways such as B cell receptor, T cell receptor, chemokine, JAK-STAT, VEGF signaling pathways, and other tumor development-associated pathways." (PMID 37351109, 2023). "High KLRB1 expression could suppress the tumor formation in the gastric cancer mouse model." (PMID 37520246, 2023). "Tscm cells, which appear to be contained in cluster 8.6 (KLRB1) on the basis of signature gene expression, have the capacity for self-renewal and to differentiate into memory and effector cells, thereby acting as a “resource” cell to replenish tumor-reactive CD8+ T cells." (PMID 35263569, 2022). "Altogether, our findings indicate that KLRB1 may influence tumor immunity mainly by mediating TILs." (PMID 35028320, 2022).
tumor (continued). "Furthermore, in humanized mouse models, inactivation of KLRB1 in tumor-infiltrating T cells led to enhanced anti-tumor killing, as evidenced by slower tumor progression, significantly increased survival time and increased infiltration of PD1-TIM3- T cells compared to unaltered T cells." (PMID 34868044, 2021). "Also, KLRB1 gene (CD161) was expressed on tumor-infiltrated NK cells, which could bind to the CLE2D ligand on tumor cells to inhibit NK cell-mediated cytotoxicity." (PMID 34177887, 2021). "Furthermore, KLRB1 was also expressed by a subset of tumor-infiltrating CD4+ and CD8+ T cells in other tumor types including melanoma, non-small cell lung cancer (NSCLC), hepatocellular carcinoma, and colorectal cancer indicated by several published scRNA-seq datasets 9-12." (PMID 34659549, 2021). "Gene expression analysis revealed higher levels of activation, cytotoxicity, and memory markers (e.g., CD69, PRF1, TNF, KLRB1, and NCR3) in iMRAS-activated CAR-iNKT cells, correlating with their enhanced tumor-killing potential." (PMID 40297706, 2025). "The scores of immunomodulatory interactions manifested a downgrade in tumor tissues, largely influenced by CLEC2D, CLEC2C, CLEC2B, and KLRB1." (PMID 40723292, 2025). "Clinical and pathologic data included age, American Joint Committee on Cancer (AJCC) pathologic tumor stage (TNM), AJCC clinical tumor stage, KLRB1 expression, and OS." (PMID 38608099, 2024). "Univariate regression analysis indicated a significant correlation between tumor number, tumor size, tumor stage, BCLC stage, AFP, and the expression of KLRB1 on CD8+ T cells and NK cells with patient recurrence and death." (PMID 38914941, 2024). "Cell communication analysis also revealed specific interactions between CD1C+ cDC2 cells and T/NK cells in multi‐primary tumours, highlighting the involvement of CLEC2B/CLEC2C molecules and KLRB1 as ligands in this interaction." (PMID 39601163, 2024). "Our data indicated that the “cold” tumor types like MB and EPN also contained the major classical immune cells, such as T cells (PTPRC, CD3D), B cells (CD79A, IGHG1, MZB1), and NK cells (KLRB1)." (PMID 38094301, 2023). "Among TME-related prognostic signature, KLRB1, SCL27A2, PXDNL, LINC02038, IGHV1-12, IGKV1OR2-108 were directly related to tumor immunity to a certain extent, reflecting the characteristics of natural killer cells, natural killer T cells and other immune cells." (PMID 36869083, 2023). "We found that compared with the existing predictive immune signal indicators TMB and degree of glycolysis, KLRB1 expression was more strongly correlated with the immune score and cytotoxicity, suggesting that the expression of KLRB1 may be more representative of tumor immunity." (PMID 35028320, 2022). "Next, we explored the correlation between KLRB1 and the biomarkers TMB and MSI that are closely related to tumor immunity and immunotherapy response." (PMID 35028320, 2022). "Recently, several reports have shown that the KLRB1 gene and its coded protein CD161 play an essential role in tumor immunity." (PMID 35028320, 2022). "The Hub gene was identified and constructed based on 6 genes (KLRB1, KLF2, S100A9,MSC,ANXA5 and IMPDH1), which will help to for a predictive analysis of the tumor immune microenvironment in HCC patients." (PMID 35992798, 2022). "While, the paired analysis showed that expression of IL26, IL17F, KLRB1, CD40LG, JCHAIN, and NFKBIZ were significantly lower in the tumor group, compared with normal tissues." (PMID 35902909, 2022). "KLRB1 was notably increased in CD8-GNLY effector T cells both in MM patients with high and low tumor infiltration, which was confirmed by flow cytometry in primary MM patient samples." (PMID 36532059, 2022). "In comparison with adjacent and precancerous tissues, we found a significant reduction of CD40+, CD27+, KLRB1+, and CCL5+ B cells (clusters 4, 9, 1, and 3, respectively) and MZB1+, DUSP1+, and CCL3+ plasma cells (clusters 5, 7, and 8) in tumor tissues." (PMID 34185431, 2021).
tumor (continued). "TIMER analysis revealed that KLRB1, SIT1, and GZMM were negatively correlated with tumor purity and positively correlated with the infiltration of B cells, neutrophils, macrophages, CD4 T cells, CD8 T cells, and dendritic cells." (PMID 33164640, 2020). "We found that KLRB1, SIT1, and GZMM were negatively correlated with tumor purity and positively correlated with the infiltration of B cells, CD4 T cells, CD8 T cells, neutrophils, macrophages, and dendritic cells." (PMID 33164640, 2020). "Single-cell expression analysis revealed that KRT5 and FABP7 were highly enriched in tumor cells, UGT2B4 was predominantly expressed in epithelial cells, BIRC3 and KLRB1 were enriched in CD8+ T cells, while MRC1 and CD209 were highly expressed in monocytes/macrophages." (PMID 40612672, 2025). "Consequently, the inactivation of KLRB1 or antibody‐mediated blockade of CD161 restores T cell metabolic capacity, thereby enhancing cytotoxicity against tumor cells and augmenting systemic antitumor immune responses." (PMID 40891683, 2025). "It was speculated that KLRB1 and KLRD1 show reduced expression in the tumor microenvironment of patients with T-ALL/T-LBL, which can lead to immune response deficits." (PMID 38464517, 2024). "Moreover, KLRB1 has a significant relationship with LUAD purity and the tumor immune microenvironment of LUAD." (PMID 38782996, 2024). "Correlative elaboration of key molecules including FCER1G, ZGMM, KIR2DL4, KIR3DH5, KLRC1, KLRB1, and FKBP5 among the 5 cell‐type clusters in evolutionary development trajectory of NKT for immune escalation against evasion of vital tumor cells and mutants was further illustrated by Violin plots." (PMID 37693048, 2023). "Moreover, the KLRB1 expression level is related to TMB and MSI and related to various immune signatures of tumor." (PMID 35028320, 2022). "Subsequently, we analyzed DEGs between tumor and normal tissues and selected the top five DEGs with the highest expression, which were SPP1, AKR1C2, AKR1B10, AGT, and EPHX1 in tumor tissues and NKG7, KLRD1, KLRB1, CCL5, and CST7 in normal tissues." (PMID 35967424, 2022). "Moreover, we studied the influence of KLRB1 expression on the tumor microenvironment (TME) and explored the relationship between KLRB1 and various immune biomarkers." (PMID 35028320, 2022). "In this model, we did not see an appreciable infiltration of CD4+ T, CD8+ T or CD161/KLRB1+ natural killer (NK) cells in the bladder/tumor." (PMID 30654801, 2019). "Moreover, KLRB1 expression exhibited a positive correlation with the expression of PDCD1 (r = 0.624), CD274 (r = 0.317), and CTLA4 (r = 0.541) under condition of tumor purity, and PDCD1 (r = 0.731), CD274 (r = 0.441), and CTLA4 (r = 0.643) under condition of age in BRCA." (PMID 37988189, 2023). "They demonstrated an enhanced anti-tumor effect of these T cells through the direct blockade of CD161, a NK cell receptor expressed on the T cells surface, or by the inactivation of its respective NK gene KLRB1, highlighting the role of CD161 and potential therapeutic intervention." (PMID 34440802, 2021). "The REP protocol preferentially expanded small clones of the CD4+ phenotype (CD4, IL7R, KLRB1) in the TME, indicating that the largest exhausted T cell clones in the tumor do not expand during the expansion protocol." (PMID 37484198, 2023). "However, unlike in the human tumor environment, the human-like CD8 GZMB+ clusters in mouse hardly expressed Lag3 or Klrb1." (PMID 38245530, 2024).
cancer (84 papers, 2013 to 2026). A tumor composed of atypical neoplastic, often pleomorphic cells that invade other tissues. "Numerous studies have illustrated the association of KLRB1 expression with the prognosis of various cancers." (PMID 38596682, 2024). "Using The Cancer Genome Atlas dataset, a 5-CD8Gs risk model (KLRB1, FYN, IL2RG, FCER1G, and DGKZ) was constructed, which was verified in International Cancer Genome Consortium and gene expression omnibus datasets." (PMID 38489709, 2024). "In recent years, killer cell lectin-like receptor B1 (KLRB1) encoded by the CD161 gene has been identified, with expression in both NK cells and T cell subset, and has been found to play a significant role in cancer progression." (PMID 37988189, 2023). "Expression of killer cell lectin-like receptor B1 (KLRB1), the gene encoding the cell surface molecule CD161, is associated with favorable prognosis in many cancers." (PMID 35039463, 2022). "Patients with high KLRB1 expression have more promising prognosis in most cancers, and its expression level is mainly associated with TMB, MSI, and several immune signals of tumors." (PMID 35992798, 2022). "KLRB1, an NK cell receptor, plays an essential role in regulating the ability of the immune system to fight exogenous and self-diseases and is significantly associated with cancer progression." (PMID 38782996, 2024). "KLRB1 is associated with a better prognosis in most types of cancer." (PMID 38780041, 2024). "Killer cell lectin-like receptor B1 (KLRB1) is implicated in cancer progression and immunity." (PMID 38782996, 2024). "In addition, GSEA results showed that KLRB1 was significantly associated with PD-L1 expression and PD-1 checkpoint pathway in cancer." (PMID 37988189, 2023). "The expression of KLRB1 was closely associated with favorable outcomes in a pan-cancer research." (PMID 35443644, 2022). "Moreover, a positive correlation was obtained for Killer cell lectinlike receptor B1 (KLRB1), a T-cell and NK-cell marker gene associated with favorable prognosis across a broad variety of cancers." (PMID 34503273, 2021). "Previous study has also shown that KLRB1 mRNA is significantly downregulated in most cancer tissues compared to their corresponding normal tissues." (PMID 40115278, 2025). "Reduced KLRB1 expression has a significant positive correlation with diagnosis, poor prognosis, and immunity to cancer in patients with LUAD." (PMID 38782996, 2024). "To compare KLRB1 expression in human cancers, we used the TCGA database to assess how KLRB1 is expressed in multiple types of cancers." (PMID 38608099, 2024). "In short, reduced KLRB1 expression has a significant positive correlation with the diagnosis, poor prognosis, and cancer immunity of patients with LUAD." (PMID 38782996, 2024). "First, it was determined the expression level of KLRB1 in TGCT using The Cancer Genome Atlas (TCGA) (The Cancer Genome Atlas) dataset and GTEx (Genotype-Tissue Expression) dataset." (PMID 38608099, 2024). "We also observed that KLRB1 expression levels were significantly down-regulated in the cancer tissues of Asians with LUAD compared to those of Caucasian or African-American patients." (PMID 38782996, 2024). "Prior studies have reported KLRB1 as a potential prognostic and immunological marker across tumors using pan-cancer analysis." (PMID 37520246, 2023). "In this study, we utilized cancer tissues from the TCGA database to investigate the correlation between KLRB1 expression levels and various immune parameters." (PMID 37988189, 2023). "GSEA analysis revealed that KLRB1 was involved in various biological functions and pathways related to immune response, and cancer." (PMID 37988189, 2023). "Except for LAML, in the remaining 32 cancers, the expression level of KLRB1 was positively correlated with the immune score." (PMID 35028320, 2022). "For doxorubicin, 15 types of cancer patients with different expression levels of KLRB1 were predicted to exhibit different therapeutic effects." (PMID 35028320, 2022).
cancer (continued). "Consistent with TCGA results, except for KIRP, KLRB1 showed low expression in the other ten cancers." (PMID 35028320, 2022). "Our study provides strong evidence for the prognostic and immunological value of KLRB1 in various tumors through a comprehensive pan-cancer analysis." (PMID 35028320, 2022). "After analyzing the correlation between multiple immune signatures and KLRB1, we found that the expression level of KLRB1 in pan-cancer was the most consistent with TIL infiltration, in terms of immune CYT, HLA expression, and IFN response." (PMID 35028320, 2022). "At present, KLRB1 is believed to affect tumorigenesis and development by regulating the cytotoxicity of NK cells in several cancers." (PMID 35028320, 2022). "For patients with either high or low expression of KLRB1, the expression of immune checkpoint genes was also significantly different, as patients with higher expression of KLRB1 had higher levels of immune checkpoint gene expression across 32 cancers." (PMID 35028320, 2022). "Concurrently, the results showed the Gene Set Enrichment Analysis (GSEA) of KLRB1 of each “state” in cancer cells and T cells, respectively." (PMID 36660546, 2022). "The high KLRB1 expression level was observed in cancer cells in 1 and 5 states, and high KLRB1 expression was observed in T cells in 7, 8, and 9 states." (PMID 36660546, 2022). "We also found that the expression of KLRB1 was positively correlated with lymphoid cells in almost all cancers." (PMID 35028320, 2022). "At the same time, KLRB1 expression can reflect the sensitivity of cancer patients to chemotherapy drugs." (PMID 35028320, 2022). "Among the 33 cancers, 15 cancers were found to have a statistically significant differential expression of KLRB1 compared with normal samples." (PMID 35028320, 2022). "Our findings showed that the expression of KLRB1 in 19 cancers was significantly correlated with TMB, and most were negatively correlated." (PMID 35028320, 2022). "DNA methylation is abnormal in all forms of cancer; we found that the expression levels of KLRB1 and marker genes of T cells and macrophages were principally negatively correlated with methylation and only minority positive correlations." (PMID 36660546, 2022). "This is certainly true in most human cancers where KLRB1 coding for CD161 was found the most favorable prognostic gene in a meta-analysis of expression signatures from 18 000 human tumors across 39 malignancies." (PMID 35185935, 2022). "Except for LAML, KLRB1 showed a high potential for predicting the immune response in all 33 cancers." (PMID 35028320, 2022). "In 33 cancers, the expression of KLRB1 was significantly correlated with these immune signatures, and most were positively correlated." (PMID 35028320, 2022). "For cisplatin, in 17 cancers, the expression of KLRB1 variably affected the patients' sensitivity to the drug." (PMID 35028320, 2022). "The expression levels of JUN, SFN, HSPB1, and CD47 in cancer cells and the expression levels of KLRB1, CD48, GZMK, and LY6E in CD8+ T cells were consistent with the scRNA-seq results." (PMID 33083004, 2020). "Decreased KLRB1 expression in BRCA may compromise cancer immunity and lead to an unfavorable prognosis." (PMID 40115278, 2025). "Additionally, our analysis showed that KLRB1 expression levels were significantly down-regulated in the cancer tissues of patients with T2, T3, and T4 stages of LUAD, compared to those of patients with T1 stage LUAD." (PMID 38782996, 2024). "Similarly, KLRB1 expression levels were significantly down-regulated in the cancer tissues of patients with M1 stage LUAD compared to those of patients with M0 stage LUAD." (PMID 38782996, 2024).